RBPJL (recombination signal binding protein for immunoglobulin kappa J region like)
Description:
Putative transcription factor, which cooperates with EBNA2 to activate transcription.
Synonyms: RBPL; RBPSUHL; RBP-L; SUH; SUHL
Tractability: PROTAC: ubiquitination databases record sites on it.
Gene: Protein-coding gene on chromosome 20 (45,306,840 to 45,317,824, forward strand). Ensembl gene ENSG00000124232.
Subcellular location: Nucleus
Gene Ontology:
Molecular function: protein binding; DNA-binding transcription factor activity; DNA-binding transcription factor activity, RNA polymerase II-specific; RNA polymerase II cis-regulatory region sequence-specific DNA binding; chromatin binding; DNA binding; DNA-binding transcription activator activity, RNA polymerase II-specific; RNA polymerase II transcription regulatory region sequence-specific DNA binding
Biological process: signal transduction; positive regulation of transcription by RNA polymerase II; regulation of DNA-templated transcription; regulation of transcription by RNA polymerase II
Cellular component: chromatin; nucleus; transcription regulator complex
Genetic constraint (gnomAD): Loss-of-function variants: 50 observed, 58.14 expected, observed/expected ratio (o/e) 0.86, 90% interval 0.68 to 1.09. The upper end of that interval is the gene's LOEUF score, 1.09, which puts it in group 4 of 6, group 1 being the genes least tolerant of losing a copy. Missense variants: 677 observed, 714.21 expected, observed/expected ratio (o/e) 0.95, 90% interval 0.89 to 1.01. Synonymous variants: 300 observed, 307.57 expected, observed/expected ratio (o/e) 0.98, 90% interval 0.89 to 1.07.
Homologues: Orthologues: chimpanzee RBPJL (99% identical), macaque RBPJL (97% identical), dog RBPJL (91% identical), guinea pig RBPJL (91% identical), pig RBPJL (91% identical), mouse Rbpjl (88% identical), rat Rbpjl (88% identical), zebrafish rbpjl (59% identical), Caenorhabditis elegans lag-1 (42% identical). Paralogues in human: RBPJ (48% identical).
Diseases named in the same sentence as RBPJL in open-access papers:
RBPJL is named in the same sentence as 16 diseases in open-access papers, as found by Europe PMC text mining. Sharing a sentence is not in itself a finding about the gene and the disease. The quoted sentences say what the papers report.
pancreatic cancer (3 papers, 2017 to 2023). "The protein products from AGR2, CEAMAN6, GNMT, PDIA2, POSTN, RBPJL and S100P have been reported as potential diagnostic and prognostic biomarkers for pancreatic cancer or have demonstrated to be involved in either pancreatic cancer, initiation, migration, invasion, metastasis, or chemoresistance." (PMID 36812168, 2023). "RBPJL is specifically expressed in the exocrine pancreas, whereas it is mostly undetectable in pancreatic tumour cell lines." (PMID 34638511, 2021). "Using this approach and verifying the data using individual gene expression data, we found that AGR2, CEACAM6, GNMT, PDIA2, POSTN, RBPJL, and S100P are upregulated in pancreatic tumor tissue as compared to non-tumor tissue from Black and White patients." (PMID 36812168, 2023).
acute monocytic leukemia (1 paper, 2021). Acute monoblastic leukemia (AML-M5), is one of the most common subtypes of acute myeloid leukemia (AML) that is either comprised of more than 80% of monoblasts (AML-M5a) or 30-80% monoblasts with (pro)monocytic differentiation (AML-M5b). "In THP-1 cells (acute monocytic leukemia), RBPJL expression was detectable, but less than that of RBPJ." (PMID 34638511, 2021).
acute promyelocytic leukemia (1 paper, 2021). An aggressive form of acute myeloid leukemia (AML), characterized by arrest of leukocyte differentiation at the promyelocyte stage, due to a specific chromosomal translocation t(15;17) in myeloid cells. "Surprisingly, in selected myeloid leukemia cell lines U937 (histiocytic lymphoma) and NB-4 (acute promyelocytic leukemia) we found RBPJL expression levels comparable to that of RBPJ." (PMID 34638511, 2021).
colon cancer (1 paper, 2021). "In an unrelated colon cancer cell line, HCT-116, RBPJL was barely detectable." (PMID 34638511, 2021).
esophageal squamous cell carcinoma (1 paper, 2020). Esophageal squamous cell carcinoma (ESCC) is a type of esophageal carcinoma (EC) that can affect any part of the esophagus, but is usually located in the upper or middle third. "We report for the first time that RBPJL (p.P476S) promotes tumor growth in oesophageal squamous cell carcinoma (ESCC) and inhibits the efficacy of anti‐PD‐1 therapy by blunting T‐cell responses." (PMID 32994998, 2020).
myeloid leukemia (1 paper, 2021). A clonal proliferation of myeloid cells and their precursors in the bone marrow, peripheral blood, and spleen. "Expression levels of RBPJL are increased in certain cell lines, such as myeloid leukemia cell lines NB-4, U-937 and THP-1." (PMID 34638511, 2021). "Thus, it is possible that RBPJL offers a selective advantage for certain subtypes of myeloid leukemia, even in the absence of PTF1a, most probably deregulating Notch target genes." (PMID 34638511, 2021).
tumor (5 papers, 2020 to 2025). "Based on these clinical and translational findings, we reported for the first time that the p.P476S mutation of RBPJL promotes tumor growth in ESCC and inhibits the efficacy of anti‐PD‐1 therapy in ESCC patients." (PMID 32994998, 2020). "We report for the first time that RBPJL (p.P476S) promotes tumor growth in ESCC and inhibits the efficacy of anti‐PD‐1 therapy through blunting T‐cell responses." (PMID 32994998, 2020). "In addition, compared with the tumors in the RBPJL (p.P476S) group, RBPJL‐overexpressing tumors showed a better response to toripalimab, as reflected by the dramatic reduction in tumor weight and volume." (PMID 32994998, 2020). "Compared with IgG, toripalimab significantly increased tumor‐infiltrating CD4+ and CD8+ T cells and inhibited tumor cell proliferation, as indicated by the downregulation of Ki67 expression, while the RBPJL‐overexpressing group showed more infiltration in the presence of toripalimab." (PMID 32994998, 2020). "The identification RBPJL mutation was intriguing, and we hypothesised that RBPJL (p.P476S) might not be sufficient to initiate ESCC predisposition but plays a role in tumor progression." (PMID 32994998, 2020). "Since tumor cells resemble a ductal fate in PDAC, we hypothesized that RBPJL not only is a pancreas specific marker, but more specifically, is an acinar marker of the pancreas." (PMID 34638511, 2021). "Similarly, the RBPJL‐overexpressing group, not the RBPJL (p.P476S) group, exhibited significant tumor inhibitory effects in the absence of toripalimab." (PMID 32994998, 2020). "Similarly, RBPJL‐overexpressing group exhibited greater infiltration of CD4+ and CD8+ T cells and tumor inhibition than the IgG group in the absence of toripalimab." (PMID 32994998, 2020).
cancer (4 papers, 2019 to 2021). A tumor composed of atypical neoplastic, often pleomorphic cells that invade other tissues. "Thus, it will be interesting to see whether RBPJL expression can be associated with certain types of cancer in the clinical setting." (PMID 34638511, 2021). "To gain insight on the role of RBPJL in cancer, we looked for the expression of RBPJL in several cell lines." (PMID 34638511, 2021). "Western blot analysis showed that RBPJL markedly increased the expression of phosphorylated IκBα and NF‐κB/p65 compared with EV control, thus facilitating NF‐κB nuclear translocation in cancer cells." (PMID 32994998, 2020). "An upregulated expression of RBPJL indicates that the Notch signaling pathway is active in the case of NPC, and it will increase the proliferation and progression of cancer cells." (PMID 32986356, 2020). "GLI3, SMURF1, RBPJL, JAG1, LFNG and DTX2 were some of the most amplified genes present in at least 18 cancers." (PMID 31523055, 2019). "Thus, it is tempting to speculate that the expression of RBPJL, which only represses but does not coactivate together with Notch, might be a selection advantage in certain cancer types." (PMID 34638511, 2021).
metabolism disorders (1 paper, 2021). "Based on the pseudo-temporal continuum profile, we identified the TF (ALX4, HINFP, CEBPA, CEBPB, DMBX1, MLXIPL, ONECUT1, and RBPJL) and depicted the regulated kernel genes co-networks, which were subjected to the metabolism disorders." (PMID 33462196, 2021).
RBPJL also shares sentences with these, for which no sentence is quoted: infection (2 papers); diabetes (1); dwarfism (1); histiocytic lymphoma (1); leukemia (1); oesophageal cancer (1); pancreatitis (1).